MMP2 (matrix metallopeptidase 2)
Diseases named in the same sentence as MMP2 in open-access papers (continued):
Sharing a sentence is not in itself a finding about the gene and the disease.
Cerebral ischemia (continued). "MMP-2/-9 are mainly secreted by resident or inflammatory cells into the extracellular surroundings (ECF-MMPs) to degrade extracellular matrix, such as tight junction proteins between endothelial cells, which leads to BBB disruption after cerebral ischemia." (PMID 37962463, 2023). "Of note, MMP-2/-9 dKO mice were studied in non-fibrosis related conditions like cancer, cerebral ischemia or antibody-induced arthritis." (PMID 35804363, 2022). "For example, both MMP2 and MMP9 downregulated ZO-1 expression and enhanced BBB permeability in response to focal cerebral ischemia-reperfusion injury, but MMP9 deficiency did not reduce disruption of the BBB during viral encephalomyelitis." (PMID 33859779, 2021). "Estrogens also could modulate the activity of MMPs such as MMP-2 and MMP-9 in ovariectomized rats under cerebral ischemia-reperfusion injury." (PMID 35432799, 2021). "Three in MMP family members, MMP2, MMP9 (referred to as the gelatinases), and MMP3, are thought to be activated within the ischemic lesion where they are critical to injury progression during and after cerebral ischemia." (PMID 30723388, 2019). "To assess the protective effects of AGNHW on the BBB integrity in the cerebral ischemia–reperfusion injury, we extracted the microvessels in the ipsilateral sides of the ischemic brains and examined the expression of MMP-9, MMP-2, and TJ proteins including ZO-1 and claudin-5." (PMID 31191319, 2019). "Evidences found that the expression and activity of MMP‐9 in the ischemic brain tissue increased significantly in the early stage of cerebral ischemia/reperfusion, while MMP‐2 showed no significant change (Liu, Hendren, Qin, & Liu, 2009)." (PMID 31566928, 2019). "The expression of MMPs, especially MMP2, MMP9 and MMP10, is induced by cerebral ischemia." (PMID 21541054, 2011). "We found that, unlike MMP-9, MMP-2 was constantly expressed at low levels in the brain tissue of both wild-type and gp91phox knockout mice, and its expression was not affected by cerebral ischemia and reperfusion or gp91phox knockout." (PMID 22146586, 2011). "Thus, in the present study, we sought to investigate the effects of XXMD on cerebral ischemia and reperfusion injury and to determine whether XXMD could attenuate BBB disruption by inhibiting the expression of MMP-9, MMP-2, and VEGF." (PMID 23710225, 2013). "Further, both MMP-2 and MMP-9 may attack the components of the basal lamina around the cerebral blood vessels, such as type IV collagen, laminin, and fibronectin, which contribute to the hemorrhagic transformation during the early stage of cerebral ischemia and reperfusion." (PMID 39273389, 2024). "In the present study, we found an increase in both MMP-2 and MMP-9 mRNA and a clear increase in MMP-9 activity in Poldip-2+/+ mice but not in Poldip2+/− mice, implying that reduction in MMP activity may contribute to the reduced BBB permeability in Poldip2+/− mice after cerebral ischemia." (PMID 29452577, 2018). "Our recent studies showed that 2-h cerebral ischemia induced BBB damage in non-infarcted area and secreted matrix metalloproteinase-2 (MMP-2) accounted for this disruption." (PMID 28855859, 2017).
fibrosis (53 papers, 2010 to 2025). the formation of excess fibrous connective tissue in an organ or tissue in a reparative or reactive process. "Specifically, MMP–2 (Gelatinase A) expression was found to have high fibrosis/cirrhosis diagnostic accuracy with many fold increase in fibrotic/cirrhotic liver compared to normal one6." (PMID 35831335, 2022). "Because matrix metalloproteinase-2 (MMP2) and matrix metalloproteinase-9 (MMP9) are associated with fibrosis in diabetic cardiomyopathy, we examined the expression and activity of MMP2 and MMP9." (PMID 34385917, 2021). "Likewise, in vivo studies on the loss of β1-integrins showed increased JNK activity was associated with increased MMP-2 activity, which corresponded with cardiac fibrosis remodeling in this setting." (PMID 33806765, 2021). "Reduction in hyperlipidemia‐induced cardiac damage were observed after luteolin treatment via suppression of lipid deposition (LOX‐1 and CD36) and cardiac fibrosis (MMP2, MMP9, Collagen I, Collagen III, and TGF‐β)." (PMID 39830909, 2025). "Based on the observed strong induction of MMP-2 and -9 in both human lung explant tissue of ILD patients and mice with established fibrosis, we determined what effect single MMP-2 or MMP-9 knockout would have on AdTGF-β1 induced lung fibrosis in mice." (PMID 35804363, 2022). "Studies have found that GAS5 can attenuate cardiac fibrosis by regulating PTEN/MMP-2 signaling pathway and improve cardiac function by inhibiting Wnt/β-catenin signaling pathway." (PMID 35619068, 2022). "Curcumin was also shown to suppress the antagonistic target of TIMP1, matrix metalloproteinase-2 (MMP-2); MMP2 promotes cardiac fibrosis and dysfunction." (PMID 32503339, 2020). "In contrast, the expression levels of cardiac fibrosis-related proteins such as MMP-2/9, TGF-β1, and p-Smad2/3 in the hearts of MI rats were higher than those in sham hearts." (PMID 30050588, 2018). "In some fibrosis models, MMP-2, MMP-9, and MMP-13 have a lower expression and concentration following treatment with MSCs." (PMID 25132856, 2014). "The CK-18 M30 and MMP-2 values of patients whose liver biopsy revealed a fibrosis stage of 1, 2, 3, 4, or 5 were higher than the CK-18 M30 and MMP-2 values of controls ( P = 0.01, P = 0.01, P = 0.01, P = 0.001, and P = 0.01, respectively)." (PMID 24032040, 2013). "Meanwhile, the cardiac fibrosis is also promoted with the featured phenotype of interstitial and perivascular fibrosis, signatured with upregulated Col1a1, Col3a1 and Tgfb expression, along with a significant increase of MMP-2 and surge upregulated active-MMP-9." (PMID 36834504, 2023). "This study highlights the association of α-smooth muscle actin (α-SMA), a marker of activation of hepatic stellate cells, pro-MMP2, TIMP1 and TIMP2 with severity of fibrosis in NAFLD patients, whereas pro-MMP9 is rather associated with the severity of inflammation." (PMID 37445827, 2023). "Increased pro‐MMP‐2 activity has been detected in BALF of rats with bleomycin‐induced fibrosis." (PMID 33274549, 2021). "Recent data have shown an ongoing remodelling activity of MMP-2 in advanced human NAFLD fibrosis." (PMID 30965590, 2019). "MMP-2 has angiogenic activity; increased angiogenesis has been detected in the area of collagen accumulation in severely hypertrophied LF and is responsible for LF fibrosis." (PMID 30067795, 2018). "Fibrosis might be mediated by increased atrial expression of IL-6 and decreased atrial expression of MMP-2 with the subsequent decline in collagen-degradation." (PMID 24775918, 2014). "In addition, Ror2+/− mice exhibited decreased MMP2 levels in damaged kidneys undergoing epithelial-to-mesenchymal transition (EMT) following unilateral ureteral obstruction-induced fibrosis." (PMID 25542006, 2014).
fibrosis (continued). "On the other hand, targeted deletion of MMP2 ameliorates myocardial remodeling in mice with chronic pressure overload 52, thus the reduced MMP2 expression in Miat-KO mice may have also potentially contributed to the attenuated cardiac fibrosis and remodeling." (PMID 34335976, 2021). "Interestingly, neither levels of MMP-2 and -9 nor activity of MMP-2 associated with the presence or absence of fibrosis or measures of lung function, such as diffusing for carbon monoxide or forced vital capacity." (PMID 31272455, 2019). "As a result of this, ISO-injured mice presented with a significant reduction in LV MMP-13/TIMP-1 (by ~ 60%), MMP-9/TIMP-1 (by ~ 55%) and MMP-2/TIMP-2 (by ~ 65%) ratios at day 14 post-injury, in line with the increased LV fibrosis in these mice." (PMID 41382190, 2025). "Zhang (2015) found that salidroside significantly reduced the expression of MMP-2 and TIMP-1 mRNA and protein (p < 0.05) and attenuated the pathological changes of paraquat-induced fibrosis in rats." (PMID 38567353, 2024). "In line with this, we found an increased ACE, MMP2, and MMP7 mRNA expression, but also reduced APEH, ECE1, MBP, and NEP in samples with an advanced fibrosis grade." (PMID 39201455, 2024). "Decreased MMP-2 and MMP-9 and increased TIMP-1 were found as part of the mechanism of developed fibrosis with IL-19 KO." (PMID 37509702, 2023). "In our study, the mRNA expression levels of MMP-2, -9, and -13, as well as TIMP 1 and 2, were significantly increased in the untreated AALD fibrosis group." (PMID 35336043, 2022). "In fibrosis mice, consistently, the expression of genes related to ECM accumulation (TIMP1, MMP3 and MMP8) were decreased and genes involved in ECM elimination (MMP2, MMP9 and MMP13) were notably upregulated after JT003 treatment." (PMID 33199780, 2020). "MMP-2, MCP-1 and TGF-β have been shown to identify patients with fibrosis and future poor renal outcomes." (PMID 28219345, 2017). "The interstitial collagenases MMP-2 and MMP-13 are upregulated during resolution of fibrosis, while TIMP-1 and TIMP-2 inhibit MMP activity." (PMID 26374068, 2015). "We found that ghrelin increased the expression of MMP2, while decreasing levels of TIMPs, the inhibitors of metalloproteinases, as compared with the CCl4 and BDL treatment fibrosis model groups." (PMID 26378522, 2015). "After MSC transplantation, the increased expression of MMP-2, MMP-9, MMP-13, and MMP-14 has been observed in several fibrosis models." (PMID 25132856, 2014). "The C4M12a1 and C4M12a3 neo-epitopes were both released by MMP-2 and MMP-9, gelatinases with a high specificity for type IV collagen and known to be up-regulated in fibrosis." (PMID 24376856, 2013). "Some of the most significantly activated canonical pathways included hepatic fibrosis/hepatic stellate cell activation (CD14, COL1A1, FGFR2, IGFBP3, MMP2, and TGFBR1), and p38 MAPK signaling pathways (CREB1, PLA2G2A, TGFBR1)." (PMID 20540791, 2010). "Most interestingly, a mouse model of bleomycin-induced fibrosis showed that the administration of human CCL18 via an adenoviral vector increased TNF-, IFNγ-, MMP-2 and MMP-9 expression and increased lymphocytosis but attenuated unexpectedly the bleomycin-induced collagen deposition." (PMID 38334630, 2024). "Next, the expression patterns of MMP‐2 and TIMP‐1 were examined in our fibrosis models." (PMID 32233073, 2020). "Additionally, the study confirmed, as would be expected, that the balanced expression of MMP-2 and TIMP1 was changed in both fibrosis models, but it was recovered by IH treatment." (PMID 31467486, 2019). "We do not think that removal of PIIINP, TIMP-1, and MMP-2 by the peritoneal membrane had a significant impact on fibrosis markers plasma levels." (PMID 31141909, 2019). "Meg, a lncRNA conserved in human and mice, promote cardiac fibrosis, upregulating MMP2 expression, while Gas5 act as negative effector by sponging miR-21, which, in turn, positively regulates the fibrotic process by PTEN/MMP2 pathway." (PMID 31435517, 2018).
fibrosis (continued). "Fibrosis may also be stimulated by upregulating the MDA/4-HNE pathway; this pathway will, in turn, upregulate pro-fibrogenic matrix metalloproteinase-2 (MMP2) and downregulate matrix metalloproteinase-1 (MMP1), two enzymes responsible for remodeling the hepatic extracellular matrix." (PMID 38214802, 2024).
Myocardial fibrosis (53 papers, 2012 to 2025). "The role of MMP-2 in the progression of myocardial fibrosis has been linked to, similarly to other CVDs, the excessive degradation of ECM." (PMID 39769454, 2024). "In a previous study, they also showed that CsA caused intense myocardial fibrosis and the increase in MMP-2, while MMP-1 and MMP-9 levels were unchanged." (PMID 35681984, 2022). "Loss of TIMP3 increased myocardial fibrosis and elevated the expression of MMP2 and MMP9 to a greater extent in iron-overloaded mice." (PMID 34722652, 2021). "Fibrotic and extracellular remodeling markers Tgfβ1, Mmp2, Timp1, Col1a1, Col3a1, fibronectin and vimentin demonstrated a complex balance underlying myocardial fibrosis at different overload stages." (PMID 31181097, 2019). "Among the MMPs family, MMP2 and MMP9 are two important members associated with myocardial fibrosis regulation." (PMID 40182630, 2025). "Inhibition of the ERK1/2 pathway has a protective effect against LPS-induced myocardial fibrosis, with a notable reduction in the expression of MMP-2 and MMP-9." (PMID 40332776, 2025). "MMP2 has been identified as a potential biomarker of myocardial fibrosis in patients with hypertrophic cardiomyopathy." (PMID 37334749, 2023). "The PPARα agonist clofibrate has a beneficial cardiac effect on ischemia/reperfusion conditions by decreasing the inflammatory response that, in turn, decreases myocardial fibrosis, the MMP-2 expression, and apoptosis." (PMID 36982395, 2023). "VDR knockout mice with myocardial fibrosis have higher expression levels of matrix metalloproteinase-2 (MMP-2) and matrix metalloproteinase-9 (MMP-9) and lower expression levels of tissue inhibitors of metalloproteinase-1 (TIMP-1)." (PMID 36771445, 2023). "Relevant studies have found that MMP-2 expression is reduced in cardiomyocytes of diabetic mice and promotes myocardial fibrosis." (PMID 35322740, 2022). "Other studies have shown that MEG3 participates in the development of myocardial fibrosis and prevents myocardial remodeling by regulating the production of MMP-2 by CFs in vitro and in vivo." (PMID 33407475, 2021). "We also demonstrated that galectin-3 and MMP-2 levels increased according to the severity of myocardial fibrosis after adjusting for confounding factors." (PMID 30413105, 2018). "Exercise can increase the content of matrix metalloproteinase-2 (Mmp-2) in obese rats, increase the degradation of collagen and inhibit the formation of myocardial fibrosis." (PMID 30559720, 2018). "We further demonstrated that RDN decreased the level of NT-BNP, improved myocardial fibrosis, and decreased the expression of MMP-2 and MMP-9." (PMID 29739333, 2018). "Expression levels of fibrosis-related factors, including α-SMA, TGF-β1, MMP-2, and collagen I, were used to ascertain the degree of myocardial fibrosis." (PMID 28684968, 2017). "The results showed that maternal inflammation can induce myocardial fibrosis in offspring during aging accompanied by an imbalance of TIMP-2/MMP2 and TGFβ expression." (PMID 26006233, 2015). "As a potential regulator of myocardial fibrosis in our model, protein levels of MMP-2 were analyzed in the four cardiac chambers." (PMID 24775918, 2014). "Elevated levels of MMP2, MMP9 and TNFα in these mice were linked to increased production of collagen types I and III by CFBs in a TGFβ-dependent manner, leading to myocardial fibrosis." (PMID 22943504, 2012). "Besides, the mRNA expression of myocardial fibrosis‐related genes (Col1a1, Col5a1, and Mmp2) was reinstated in mice administered T‐5224." (PMID 40184586, 2025). "In patients submitted for surgical myectomy, plasma MMP-2 levels reflected myocardial fibrosis." (PMID 37189412, 2023). "Furthermore, as for the balance between MMP2 and TIMP2, the decrease in MMP2/TIMP2 also verified the heavier myocardial fibrosis in maternal PH rat offspring at 14 weeks of age." (PMID 35115938, 2021).
Myocardial fibrosis (continued). "Moreover, transplantation of cell sheets consisting of myoblasts or NMCs showed a significant attenuation in myocardial fibrosis and expression of fibrosis-related genes, such as MMP2 and MMP9 as compared with the control group." (PMID 32070429, 2020). "The cardiac function parameters were evaluated by echocardiographic; the serum NT-BNP level was detected by ELISA; the degree of myocardial fibrosis was observed through masson staining; the expression of MMP-2, MMP-9 in the cardiac were got by immunohistochemistry." (PMID 29739333, 2018). "In the present OSA-model, both ACE upregulation and MMP-2 downregulation could promote myocardial fibrosis." (PMID 24775918, 2014). "Consistently, cardiac overexpression of MMP2 led to severe myocardial fibrosis." (PMID 22943504, 2012). "Further research revealed that the myocardial fibrosis indicators, including PIIINP, MMP-2, and PICP, were significantly reduced in the vericiguat group (p < 0.05)." (PMID 40680000, 2025). "The animals in the test group showed features of myocardial fibrosis and a significant increase in both VEGF and MMP-2." (PMID 38674053, 2024). "Matrix metalloproteinase 2 (MMP-2), a protein that cuts other proteins into pieces, is activated in injured myocardium inducing IRIs and myocardial fibrosis." (PMID 36678575, 2023). "The coordinated reduction of MMP-2, MMP-9 and fibroblast growth factor 21 (FGF21) incurred by resveratrol results in an advance of myocardial fibrosis induced by alcohol." (PMID 36615832, 2022). "In particular, the TGF-β2–mediated imbalance of MMP2 and TIMP2 also contributes to myocardial fibrosis." (PMID 35115938, 2021). "The MMP-2 and MMP-9 are the key players of myocardial fibrosis which have been found elevated during ISO-treatment." (PMID 33328989, 2020). "In this study, administration of QSG effectively decreased the level of serum ALD, PIIINP, MMP-2, and MMP-9 that are all closely related to myocardial fibrosis in HF." (PMID 31915683, 2019). "We then analysed the expression of fibrosis-related proteins (MMP2, MMP9 and collagen I) to determine the roles of TGF-β1/Smad and HIF-1α pathways in myocardial fibrosis." (PMID 25823960, 2015). "QSYQ inhibited the TGFβ1/Smads signaling pathway and NLRP3 inflammatory vesicle expression, and significantly suppressed monocyte infiltration and macrophage polarization toward M2, thereby inhibiting MMP-2 and MMP-9 expression and ameliorating I/R induced myocardial fibrosis." (PMID 40881586, 2025). "In addition, TNF-α directly reduces collagen synthesis in cardiomyocytes, enhances matrix metallopeptidase 2 (MMP-2) and matrix metallopeptidase 9 (MMP-9) activities, promotes collagen breakdown, and exacerbates myocardial fibrosis." (PMID 37057099, 2023). "Interestingly, an opposite course with HCD was seen between the MMP2 and MMP9 collagen-degrading proteins and the profibrotic TIMP1, suggestive of increasing myocardial fibrosis." (PMID 34449561, 2021). "Consistent with the protective effect ofNAC on cardiac pathophysiological changes, real-time RT-PCR analysis of the mRNAexpressions that related to cardiac hypertrophy and myocardial fibrosis, such asα-MHC, β-MHC, ANP, BNP, Col1a1, Col3a1, Mmp2,and Mmp9, also showed the similar trend." (PMID 27443826, 2016). "MI-induced up-regulation of fibrosis-related proteins; MMP2 and MMP9 were also suppressed by valsartan, indicating that valsartan may attenuate myocardial fibrosis after MI, consistent with in vitro results." (PMID 25823960, 2015). "The results suggest that administration of valsartan inhibited the expression of fibrosis-related proteins TGF-β, MMP-2 and MMP-9, which may reduce the accumulation of collagen and further prevent the enlargement of myocardial fibrosis." (PMID 25823960, 2015).
Myocardial fibrosis (continued). "Furthermore, the experimental results suggested that GZD could downregulate the expression levels of IL-6, IL-1β, CCL2, MMP-2, and MMP-9, thus inhibiting the inflammation and myocardial fibrosis in Dahl salt-sensitive rats." (PMID 33906674, 2021). "The data indicate that downregulated MMP9 not MMP2 may partly result in the increased protein level of Col3al, contributing to cardiac fibrosis in DCM, and FTZ alleviated myocardial fibrosis at least partially by increasing the expression of MMP9." (PMID 34621323, 2021).